TRIM24 (tripartite motif containing 24)
Diseases named in the same sentence as TRIM24 in open-access papers (continued):
Sharing a sentence is not in itself a finding about the gene and the disease.
cancer (97 papers, 2012 to 2026). A tumor composed of atypical neoplastic, often pleomorphic cells that invade other tissues. "TRIM24 overexpression has been associated with poor survival in cancer, in LUSC patients, and other tumors types." (PMID 40676628, 2025). "The physiological role of TRIM24 in cancer and its association with transcriptional regulation is well established, with numerous studies in vitro, in animal models, and in humans highlighting its importance." (PMID 40598158, 2025). "In this context, it is of note that the E3 ubiquitin ligase TRIM24 has been implicated in cancer cells to initiate TREX1 degradation by the proteasome." (PMID 40072623, 2025). "Recent evidence indicates that aberrant expression of TRIM24, functions as an oncogene, is associated with poor prognosis across various cancer types." (PMID 39160596, 2024). "Tripartit-motif-containing 24 (TRIM24) appears in inflammation associated with cancers, while the NACHT, LRR, and PYD domain-containing protein 3 (NLRP3) inflammasome are implicated in endometriosis." (PMID 38337827, 2024). "The diverse biochemical activities and aberrant expressions of TRIM24 have been implicated in its significant role in cancer, rendering it an attractive target for cancer therapy." (PMID 39160596, 2024). "TRIM24 overexpression associates with aggressive malignant phenotypes, suggesting its role in cancer stemness regulation." (PMID 36674511, 2023). "TRIM24 is claimed aberrantly activated in a variety of cancer lineages and over-expressed TRIM24 is associated with tumorigenesis and disease progression." (PMID 35105347, 2022). "TRIM24 overexpression in different cancer entities, including HNSCCs, is predominantly associated with a poor prognosis for cancer patients." (PMID 35743773, 2022). "The overexpression of TRIM24 is predominantly associated with cancer progression, inferring an oncogenic function." (PMID 33810347, 2021). "Overexpression of TRIM24 is predominantly associated with cancer progression, inferring an oncogenic function." (PMID 32731534, 2020). "Indeed, TRIM24 overexpression has been linked to poor survival outcomes in cancers such as breast, bladder, and gastric cancer." (PMID 40598158, 2025). "Moreover, TRIM24 has also been linked to regulation of glucose metabolism in cancer cells." (PMID 35803934, 2022). "However, the association between TRIM24 and cancer stemness remains largely unresolved." (PMID 33810347, 2021). "The Tripartite Motif Protein 24 (TRIM24), a well-characterized chromatin reader and transcriptional regulator in cancer, has recently emerged as a potential player in cardiac biology." (PMID 40598158, 2025). "As a significant TRIM protein, TRIM24 has been progressively investigated for its roles in various cancers, although research concerning its involvement in GC remains relatively limited." (PMID 41430038, 2025). "Given the involvement of TRIM24 in cancer progression, its PHD and BRD present promising targets for therapeutic intervention." (PMID 41243558, 2025). "Among these regulators, the Tripartite Motif protein 24 (TRIM24) has recently garnered attention as a novel player in cardiac biology, despite its well-documented role in cancer." (PMID 40598158, 2025). "TRIM24 has been extensively studied in the context of cancer, where it exhibits diverse and sometimes opposing roles in cellular proteostasis, acting as a transcriptional co-regulator depending on the cellular context." (PMID 40598158, 2025).
cancer (continued). "To determine TRIM24 expression in cancers, we firstly evaluated TRIM24 levels in TCGA pan-cancer (33 cancer types), with GTEx employed to obtain TRIM24 mRNA amounts based on the XIANTAO online tool." (PMID 41430038, 2025). "According to median expression score in carcinoma, the samples were categorized as TRIM24-high or TRIM24-low." (PMID 41430038, 2025). "In response to prolonged DNA damage, ATM phosphorylates TRIM24 at serine 768 (Ser768), initiating autoubiquitination and subsequent degradation in cancer cells." (PMID 39160596, 2024). "Elevated levels of TRIM24 have been found to be correlated with the developing cancer and the progressing of disease in various types of cancer." (PMID 38389844, 2024). "Recent findings highlight that aberrant expression of TRIM24 contributes to cancer development and progression, and this abnormal expression is associated with a poor prognosis in multiple cancers." (PMID 39160596, 2024). "Herein, we review the recent advancements in understanding the functions of TRIM24, and demonstrate the research progress in utilizing TRIM24 as a target for cancer therapy." (PMID 39160596, 2024). "Moreover, TRIM24 overexpression leads to metabolic reprogramming, activating glycolytic and tricarboxylic acid cycle gene signatures, emphasizing its role in the deregulation of cancer-associated pathways, including glucose metabolism, associated with breast tumorigenesis." (PMID 39160596, 2024). "Many studies showed TRIM24 played a crucial role in regulation of proliferation in various cancer types." (PMID 39160596, 2024). "Particularly in CRPC settings, TRIM24 collaborates with AR-dependent gene expression to enhance cancer progression." (PMID 39160596, 2024). "Inhibition of the tripartite motif-containing 24 protein (Trim24), which has been reported as a suppressor of lipid accumulation and cancer development in the liver, was most significantly associated with Ly6d expression." (PMID 37394588, 2023). "Given the limited information on ADORA1 in cancer pathophysiology, the observed anticancer effects can be attributed to the inhibition of the other two targets (TRIM24 and CDK2)." (PMID 37894709, 2023). "Although mechanisms for the development and progression of these cancers are ill-defined, TRIM24-dependent transcriptional regulation is likely involved." (PMID 36690785, 2023). "In accordance with other cancer cell lines, silencing TRIM24 by shTrim24 also attenuated hypoxia-induced proliferation and migration of PASMCs." (PMID 35653796, 2022). "More functional analyses about the intracellular and cytoplasmatic functions of TRIM24 in cancer cells and especially in HNSCC are necessary." (PMID 35743773, 2022). "Of note, It was revealed that the expression of most genes was generally consistent with results of TCGA cancer set, such as TRIM24, HMG20B, CBX6, IDH1, RCC1, RYBP, CBX7, and LBR." (PMID 36246611, 2022). "These include the SUMOylation of prolyl hydroxylase 3 (PHD3), decreasing HIF-1-induced migration and invasion of the cancer cells, and the oncogenic function of tripartite motif-containing 24 (TRIM24), a SUMO E3 ligase." (PMID 35408841, 2022). "In most studies regarding TRIM24 expression in cancer tissues, the authors focused on the nuclear overexpression of TRIM24." (PMID 35743773, 2022). "TRIM24 has various intracellular functions and was identified in other cancer entities as a poor prognostic factor for patients." (PMID 35743773, 2022). "Knowing that single-agent therapeutics often lead to resistance and relapse in human cancers, we pursued assessment of TRIM24 inhibition and degradation, using a previously reported PROTAC version of TRIM24 bromodomain inhibitor IACS-957119." (PMID 34508101, 2021).
cancer (continued). "Recent studies have reported the crucial functions of Tripartite Motif Containing 24 (TRIM24) in promoting cancer progression of GBM." (PMID 34886858, 2021). "Bromodomain-specific inhibitors were developed for TRIM24 as a potential cancer treatment; however, targeting the bromodomain alone does not always prevent chromatin binding or cellular proliferation." (PMID 34298819, 2021). "For example, TRIM24 controls AR-driven transcriptional regulation in PC but also general cancer mechanisms including EMT." (PMID 34208621, 2021). "TRIM24 and TRIM28 are generally positively associated, while TRIM33 and TRIM66 are mostly negatively associated with cancer stemness in solid tumors." (PMID 33810347, 2021). "Together, these results show that TRIM24-driven tumors express a distinct set of genes that can distinguish between metaplastic and carcinoma tumors." (PMID 34508101, 2021). "Another example of successful siRNA treatment is the tripartite motif-containing protein 24 (TRIM24), a carcinogenesis factor capable of enhancing progression and viability of different cancers." (PMID 32784981, 2020). "We offered the new evidence of cancer-promoting effects of Trim24 and developed a novel drug target for the therapy of human RCC treatment." (PMID 33336072, 2020). "In fact, efforts to identify inhibitors of TRIM bromodomains are underway, with the bromodomains present in TRIM24, 28, and 33 being of particular interest to cancer therapy." (PMID 32226386, 2020). "TRIM24 is also reported to promote cancer stemness in glioblastoma by enhancing STAT3-mediate transcriptional activation." (PMID 32226386, 2020). "In CNV, we observed that TRIM24 had more gain mutations and TRIM16 has more loss mutations in pan-cancer." (PMID 33173411, 2020). "This feature is often associated with translocation of TRIM genes and creation of oncogenic fusion products, as in the case of TRIM19/PML, TRIM27/RFP and TRIM24/TIF1α, but they can influence cancer progression also per se." (PMID 30974870, 2019). "Our data indicated that TRIM24 sensitizes HNSCC cells to glucose deprivation, suggesting TRIM24 as a potential therapeutic target for cancer metabolism." (PMID 29862279, 2018). "TRIM24 (Tripartite Motif Containing 24) is a recently identified oncogene overexpressed in various cancers." (PMID 29862279, 2018). "It is reported that TRIM24 is involved in oncoprotein fusion by chromosome translocation in various cancers including leukemia, thyroid carcinoma, and myeloproliferative syndrome." (PMID 29862279, 2018). "Our results demonstrated that TRIM24 overexpression accelerated while its knockdown inhibited cancer cell proliferation and colony formation." (PMID 29862279, 2018). "Given the previously reported function of TRIM24 to regulate cancer progress through interacting with H3K23ac8,19, we further detected the interaction between TRIM24 and H3K23ac, and revealed that they are bound in U87 and LN229 GBM cells." (PMID 29129908, 2017). "TRIM24 was reported to exert its oncogenic activities in many cancers through regulating PI3K/AKT pathways." (PMID 28114950, 2017). "TRIM BRD proteins have been linked to cancer, and the chromatin binding module including the BRD of TRIM24 has been implicated in transcription regulation of cancer-specific genes in breast and prostate cancers." (PMID 27631103, 2016). "The result shows that TRIM24 mRNA level in the cancer tissues is significantly lower (P<0.001) than that in the adjacent non-cancerous esophageal tissues (NCET)." (PMID 27689360, 2016). "Collectively, this suggests that the main function of Trim24 resides in enhancing cell proliferation, thereby contributing to critical hallmarks both of pluripotency and cancer." (PMID 27773674, 2016). "Studies show that TRIM24 protein plays different roles in different cancers, suggesting that TRIM24 protein has complex functions in development and progression of cancer." (PMID 27689360, 2016).
cancer (continued). "Using siRNAs, we attempted to knock-down the expression of the two amplified, predicted driver genes in the cell line (BRAF and TRIM24) and noted a substantial reduction in the proliferation rate of cancer cells for both genes." (PMID 25572314, 2015). "We examined the expression of Ki-67 to investigate the relationship between TRIM24 positivity and proliferative activity of cancer tissues by immunohistochemistry." (PMID 22666376, 2012). "However, our study is the first to link TRIM24 to cardiac contraction and calcium homeostasis, expanding its functional repertoire beyond cancer biology." (PMID 40598158, 2025). "The interplay between TRIM24-mediated chromatin remodeling and transcriptional control underscores its broader significance in cardiac physiology, beyond its well-established role in cancer biology." (PMID 40598158, 2025). "TRIM24 upregulation was detected in 16/33 cancer types, including GC." (PMID 41430038, 2025). "In addition, TRIM24 plays specialized roles as a signal transduction molecule, orchestrating various cellular signaling cascades in cancer cells." (PMID 39160596, 2024). "Despite studies suggesting the involvement of TRIM24 in regulating EMT in cancer cells, its specific mechanism remains unclear." (PMID 39160596, 2024). "In addition, TRIM24 was able to induce upregulation of GLUT3, a glucose transporter that further confirms the fact that TRIM24 regulates glucose metabolism, thereby promoting cancer metabolism." (PMID 37953273, 2023). "This may indicate different functions of TRIM24 in different cancer entities and subcellular compartments." (PMID 35743773, 2022). "TRIM24 is proved to be an activator for AKT activation in several cancer cell lines." (PMID 35653796, 2022). "Besides that, an increased TRIM24 expression was positively correlated with a higher nodal stage in other cancer entities." (PMID 35743773, 2022). "TRIM24 play key role in proliferation and invasion of cancer cells, but high expression of this gene might be responsible for invasion of pituitary prolactinoma cells." (PMID 33709028, 2021). "As it is feasible to design small molecule inhibitors for TRIM protein family members, as has already been established for TRIM24, therapeutic development programs may be of high importance to increase the druggable space for hormone-driven cancers." (PMID 34208621, 2021). "In addition, TRIM24 has been suggested to promote cancer progression by triggering the Wnt/β-catenin signaling pathway." (PMID 32293515, 2020). "We hypothesize that TRIM24 promotes cancer cell proliferation by activating the transcription of YAP." (PMID 32677374, 2020). "Depletion of TRIM24 impaired the ability of the cancer cells to proliferate and form colonies." (PMID 32677374, 2020). "The strategy is based on suppressing TRIM24 in cancer therapy." (PMID 32784981, 2020). "Additionally, the miR-511 expression was much lower in MGC803 and HGC-27 cells, but relatively higher in other three cancer cell lines, which was inversely correlated with TRIM24 protein expression." (PMID 28114950, 2017). "TRIM24 staining was found predominantly in nuclei, suggesting it may function as a transcriptional regulator in cancer cells as suggested in a previous study." (PMID 23717505, 2013). "However, a specific substrate for the E3 ubiquitin ligase activity of TRIM24 awaits elucidation in order to understand the molecular mechanism by which the TRIM24–Sox2 axis may impact cancer stemness in gliobastoma." (PMID 35205738, 2022).
cancer (continued). "The findings reveal a novel mechanism where H3K23ac/TRIM24 mediates EGFR-induced STAT3 activation, enhancing the oncogenic potential of the EGFR/STAT3 pathway in human cancer." (PMID 39160596, 2024). "Given that ATF3 functions in multiple pathways to regulate cancer progression, we proposed that ATF3 is a key downstream gene regulated by TRIM24 in the TRIM24‐driven Ep‐GBM‐like transformation." (PMID 38828688, 2024). "It has been demonstrated that TRIM24 regulates the NF-κB and AKT signaling pathways, thereby contributing to cancer progression and metastasis." (PMID 37953273, 2023). "The Median IHC score of TRIM24 were gradually increased in the three groups of normal ovarian tissues, EOC primary cancer tissues and metastatic tissues." (PMID 35105347, 2022). "Tripartite Motif Containing 24 (TRIM24) is an oncogenic protein and promotes proliferation in several cancer cell lines." (PMID 35653796, 2022). "TRIM24, TRIM28, TRIM33, and TRIM66 form the transcriptional intermediary factor 1 (TIF1) family of chromatin-binding proteins that are involved in DNA damage response (DDR) and show significant involvement in different cancer types." (PMID 33923045, 2021). "In contrast to TRIM24, the expression of TRIM28 positively correlates with MYC expression in several cancer types." (PMID 33810347, 2021). "As for TRIM24, it is a member of the tripartite motif (TRIM) family, and the oncogenic role of TRIM24 in carcinogenesis has been demonstrated in several cancer types." (PMID 32293515, 2020). "Other members of TRIM family proteins, such as TRIM14, TRIM24 and TRIM98 have been reported to enhance chemoresistance in certain human cancers." (PMID 31992359, 2020). "To acquire more intuitive understanding of endogenous Trim24 level, we performed immunohistochemical staining in RCC tissue and para-carcinoma tissue derived from the same patient." (PMID 33336072, 2020). "This investigation identifies a previously unrecognized mechanism, in which H3K23ac/TRIM24 functions as a mediator of EGFR/EGFRvIII activation of STAT3 signaling, thereby promoting tumorigenesis in human cancers." (PMID 29129908, 2017). "However, the function of TRIM24 in cancers is still largely unknown." (PMID 29129908, 2017). "Interestingly, some other members of the TRIM family are involved in cancer development, some of which are due to chromosomal translocations like TRIM24/TIF1a, TRIM27/RFP, and TRIM33/TIF1g, whose RBCC motifs play a critical role in cell transformation." (PMID 38611029, 2024). "The resulting antitumor activity may, in turn, be derived from the inhibition of important molecular targets involved in cancer pathogenesis, including ADORA1, CDK2, and TRIM24." (PMID 37894709, 2023). "TRIM24 has been posited as a dependency in numerous cancers, yet potent and selective ligands for the TRIM24 bromodomain do not exert effective anti-proliferative responses." (PMID 31885879, 2019). "TRIM24, as a founding member of TRIM family, has been identified as being involved in physiologic and pathological processes, including cell growth, apoptosis, invasion and cancer development." (PMID 28114950, 2017). "In our study, we demonstrated that the protein expression of TRIM24 in HCC cancer tissues was higher than in noncancerous tissues, normal tissues, and benign liver lesions tissues." (PMID 24409330, 2014). "While previous studies and public data sets showed that TRIM24 RNA is expressed across a broad range of cancers, it is not yet established whether TRIM24 plays a similar role in promoting malignancy through alterations of EMT, E2F, and metabolic pathways." (PMID 34508101, 2021). "Interestingly, the EMT scores of TRIM24-driven and non-TRIM24-driven carcinomas were not significantly different." (PMID 34508101, 2021).
cancer (continued). "The cell cycle analyses were performed in cancer cells with or without TRIM24 knockdown, and found that the percentage of G1 phase was increased in cells with TRIM24 knockdown, whereas the percentage of S phase was decreased in these cells compared with control cells." (PMID 22666376, 2012).